IFI44L (interferon induced protein 44 like)
Description:
Type I interferon-stimulated gene (ISG) that plays a critical role in antiviral and antibacterial activity. During bacterial infection, promotes macrophage differentiation and facilitates inflammatory cytokine secretion. Plays a role in the control of respiratory syncytial virus/RSV infection, reducing the ability of the virus to replicate. Exhibits a low antiviral activity against hepatitis C virus. Also acts as a feedback regulator of IFN responses by negatively regulating IKBKB and IKBKE kinase activities through interaction with FKBP5.
Synonyms: C1orf29; GS3686; TLDC5B
Tractability: No criterion of Open Targets' tractability assessment is met for any kind of drug.
Gene: Protein-coding gene on chromosome 1 (78,619,902 to 78,646,145, forward strand). Ensembl gene ENSG00000137959.
Subcellular location: Cytoplasm
Subcellular location (Human Protein Atlas): Nucleoplasm
Pathways (Reactome):
Immune System: Modulation of host responses by IFN-stimulated genes
Gene Ontology:
Biological process: defense response to virus; immune response; response to virus
Cellular component: cytosol; cytoplasm
Genetic constraint (gnomAD): Loss-of-function variants: 22 observed, 24.81 expected, observed/expected ratio (o/e) 0.89, 90% interval 0.63 to 1.27. The upper end of that interval is the gene's LOEUF score, 1.27, which puts it in group 5 of 6, group 1 being the genes least tolerant of losing a copy. Missense variants: 470 observed, 423.35 expected, observed/expected ratio (o/e) 1.11, 90% interval 1.03 to 1.2. Synonymous variants: 148 observed, 144.36 expected, observed/expected ratio (o/e) 1.03, 90% interval 0.9 to 1.17.
Homologues: Orthologues: chimpanzee IFI44L (98% identical), macaque IFI44L (90% identical), pig IFI44L (61% identical), rabbit IFI44L (60% identical), rat Ifi44l (54% identical), zebrafish si:ch211-197g15.5 (35% identical), zebrafish si:ch211-197g15.9 (35% identical), zebrafish ifi44c2 (34% identical), zebrafish ifi44f4 (34% identical), zebrafish ifi44c1 (33% identical), zebrafish ifi44f1 (33% identical), zebrafish ifi44f3 (33% identical), and 10 more. Paralogues in human: IFI44 (43% identical).
Diseases named in the same sentence as IFI44L in open-access papers:
IFI44L is named in the same sentence as 100 diseases in open-access papers, as found by Europe PMC text mining. Sharing a sentence is not in itself a finding about the gene and the disease. The quoted sentences say what the papers report.
viral infection (47 papers, 2011 to 2025). "IFI44L is upregulated in the blood of viral-infected patients and has been proposed as a promising diagnostic biomarker for viral infections." (PMID 39861921, 2025). "We screened for differentially expressed genes associated with bacterial or viral infections (IFI44L, PI3 and ITGB2) and compared the expression levels of the genes in different infection subgroups." (PMID 41050698, 2025). "IFN-induced protein 44-like (IFI44L) plays a role in the immune response to viral infections and has been implicated in the pathogenesis of SLE." (PMID 38885315, 2024). "This study is important because IFI44 and IFI44L are upregulated after a wide range of viral infections, and IFI44L can serve as a diagnostic biomarker of viral infection." (PMID 32611756, 2020). "Although severe viral infection may cause IFI44L downregulation, the two-transcript model incorporating PI3 effectively resolves this confounding factor to ensure diagnostic accuracy." (PMID 41050698, 2025). "In this study, we investigated whether whole-blood RNA expression of the genes FAM89A and IFI44L from children with FN could be used as a diagnostic tool to discriminate bacterial from viral infections." (PMID 37371198, 2023). "Interferon-induced protein 44-like (IFI44L) is an antiviral ISG with mechanisms of action dependent on the specific context of viral infections." (PMID 39861921, 2025). "PARP12 is a representative ISG that inhibits viral replication via ADP-ribosylation, while IFI44L is an interferon-inducible gene that is upregulated upon viral infection." (PMID 41465783, 2025). "Acting as a feedback regulator of the IFN response, IFI44L potentially promotes viral replication by modulating the innate immune response following viral infection." (PMID 37630661, 2023). "Interferon (IFN)-induced protein 44-like (IFI44L) gene exhibits a negative regulatory ability in the innate immune response induced upon viral infection." (PMID 35928229, 2022). "Among the genes, IFI44L is often expressed as a response to viral infections, which evokes extensive immunomodulation." (PMID 35222683, 2022). "Five hub genes shared by RA, COVID-19, and SAB were IFI44, OAS1, IFI44L, ISG15, and HERC5, and they were found to be closely associated with the immune system response to viral infection and bacterial infection using Metascape analysis." (PMID 36189314, 2022). "As a feedback regulator of IFN responses, IFI44L can facilitate virus replication via modulating innate immune responses induced after virus infections." (PMID 35958619, 2022). "cg03607951 is located in IFI44L which is involved in innate response to viral infection and several systemic autoimmune diseases." (PMID 35798818, 2022). "IFNs-induced protein 44-like (IFI44L) was identified as negatively modulator for innate immune response induced by virus infection, which interacts with FKBP5 to decrease the phosphorylation of IRF-3 and NF-B mediated by IKK and IKK, respectively." (PMID 34884921, 2021). "As we all know, IFI44L played a crucial role in anti-virus processes and is competent to be a biomarker in diagnosis of viral infection." (PMID 35047409, 2021). "These antiviral genes involved in the innate immune response as part of the host defence response to clear viral infections were specifically upregulated, including IFI44L and TRIM22 in M. tuberculosis-infected macrophages." (PMID 34722780, 2021). "IFIT2 and IFI44L have previously been identified as ISGs during viral infection, supporting our hypothesis that VILMIR may regulate the host interferon response." (PMID 40130878, 2025). "Moreover, previous studies have implicatedsimilar ISGs, including OASL, IFI27, IFIT1 and IFI44L, in the pathogenesis of other viral infections such as hepatitis C virus (HCV),suggesting a broader role for these genes in viral-induced liver diseases." (PMID 40322700, 2025). "IFI44L negatively regulates the innate immune response induced by viral infection." (PMID 35928229, 2022).
viral infection (continued). "Expression of two antiviral proteins was measured from which we expected different expression patterns: MX1, a protein rapidly induced by type‐I interferon which is interfering with viral replication, as well as IFI44L, recently shown to negatively regulate cellular responses after virus infections." (PMID 34169553, 2022). "During viral infection, the upregulation of IFI44L is commonly seen." (PMID 33494515, 2021). "The function and pathway enrichment analyses of M. tuberculosis H37Rv-infected macrophage by RNA-seq demonstrated that gene enrichment was closely associated with viral infection genes, including TRIM22, IFIT1, IFI44L, and IFI44, consistent with M. tuberculosis being an intracellular pathogen." (PMID 34722780, 2021). "The data presented here explore how the ISGs IFI44 and IFI44L modulate viral infection." (PMID 32611756, 2020). "Increased levels of IFI44L mRNA are also part of the cellular response to viral infection." (PMID 24755989, 2014). "Though the function of FAM89A gene is not well studied, researches indicated that FAM89A gene, together with IFI44L gene, was capable of differentiating between bacterial and viral infections with high sensibility and specificity, suggesting that FAM89A gene might be involved in immune response." (PMID 36451823, 2022). "Therefore, the mRNA expression of IFI44L can be used as an early indicator of virus infection." (PMID 35620480, 2022). "The highest ratio in this set was two-fold and out of the top 10 specificities, 7 were in the Type I interferon signature (IFITM3, MX1, IFI6, IFI44L, ISG15, OAS1, IFIT3) and one encodes a protein that is activated by dsRNA as might be present in a viral infection (EIF2AK2)." (PMID 21366908, 2011). "The observed elevation of ISGs, encompassing ISG15, IFI6, IFIT1, IFIT2, IFIT3, IFI44L, and IFITM3, highlights SARS-CoV-2’s ability to activate the host’s interferon response—a critical defence mechanism against viral infection." (PMID 39940816, 2025). "IFI44L and PI3 transcript levels are robust classifiers to discriminate bacterial from viral infection in UC-OI, and measuring its levels appears to be predictive infection progression and treatment outcome in UC patients over time." (PMID 41050698, 2025). "Moreover, differential upregulation of IFI44L has been found in cells or tissues infected by many other viruses such as Hepatitis E virus (HEV), Influenza A virus (IAV), and rhinoviruses (RV), indicating that IFI44L holds significant promise for treating diseases caused by viral infections." (PMID 39737399, 2024). "VirSig was defined as the signature of the host response to viral infection using the average expression of five representative genes, including IFI27, RSAD2, IFI44L, ISG15 and IFITM3." (PMID 38790931, 2024). "IFI44L is a paralog gene of IFI44 and functions as a regulator of cell apoptosis, virus infection, and congenital immune response." (PMID 35620480, 2022). "IFI44L participates in the antiviral process of IFN-mediated innate immune response and is a confirmed marker of early viral infection." (PMID 35620480, 2022). "The top genes in the individual LIMMA analyses that were differentially expressed in peripheral blood samples of patients hospitalized with viral infection vs. bacterial (baseline in the model) infection were ISG15, TIMM10, IFI27, IFI44L and OAS2." (PMID 34593881, 2021). "It is well known that type-I IFN induces potent cellular defense against viral infection mediated by up-regulation of ISGs like IFI44, IFI44L, and HERC5." (PMID 31749827, 2019). "IFI44L is a paralog of IFI44, a well-known immune response gene induced in response to viral infections." (PMID 30296270, 2018). "Differential expressed genes analysis of IFI44L, PI3 and ITGB2 in bacterial and viral infections." (PMID 41050698, 2025). "Ifi44l represses the interferon response, protecting the host from the negative effects of the innate immune response during viral infection." (PMID 38696518, 2024).
viral infection (continued). "Among non-tumor diseases, IFI44L was found to be strongly associated with immune disorders, especially SLE, SS, rheumatoid arthritis (RA) and various viral infectious diseases." (PMID 39737399, 2024). "We observed that adult patients with epileptic seizures had peripheral whole blood that included miR-654-3p, miR-323a-3p, miR-323b, miR-3283p, miR-342-5p, miR-150-5p, miR-3395p and IFIT3, IFIT1, IFI44L, OAS3, and LY6E in the pathways connected to viral infection." (PMID 36172025, 2022). "Besides the involvement of IFI44L in tumors, it is frequently observed in non-tumor conditions, primarily immune disorders, viral infections, and bacterial infectious diseases." (PMID 39737399, 2024). "Previous studies indicated a promising role of interferon-induced protein 44-like (IFI44L) in antiviral response and antitumour and inflammatory responses on innate immunity and a critical role it plays in the efficient and rapid limitation of viral infections." (PMID 34722780, 2021). "Besides, IFI44L has been found to be upregulated after a wide range of viral infection and is involved in antiviral and anti-proliferative respiratory syncytial virus (RSV) infection procedure, suggesting that the IFI44L may serve as a promising biomarker of viral infection." (PMID 35047409, 2021). "In particular, 8 genes (Mx1, EPSTI1, XAF1, IFI44L, GBP1, SAMD9, SAMD9L, and CMPK2) were expressed in the highly resistant cell lines HPAF-II and Hs766T but not the highly permissive cell lines MIA PaCa-2 and Capan-1 in the absence of virus infection." (PMID 27533247, 2016).
COVID-19 (34 papers, 2020 to 2025). A disease caused by infection with severe acute respiratory syndrome coronavirus 2. "It confirmed previously reported associations with IFI44L and the involvement of interferon-responsive genes in the underlying pathophysiology of COVID-19 and showed that such signals can be identified months after the infection." (PMID 35798818, 2022). "Several IFN-related genes, such as SPATS2L, OAS2, ISG15, ZBP1, and IFI44L, exhibited similar patterns of upregulation across both dengue and COVID-19 datasets, while others, such as AIM2 and RTP4, showed distinct regulation." (PMID 38444851, 2024). "Although IFN genes such as IFI27 and IFI44L are also highly expressed in various cell types in COVID-19 samples, monocytes contributed the most among PBMCs, suggesting its active involvement in interferon response." (PMID 38268924, 2023). "We also identified that the interferon-stimulated genes (ISGs) such as IFIT2, IFI6, and IFI44L were upregulated in COVID-19 patients." (PMID 35922752, 2022). "Additionally, interferon signaling in B-cells was elevated in patients without pulmonary injury, indicated by increased expression of MX130, XAF131, and IFI44L compared to patients with pneumonic COVID-19." (PMID 35197461, 2022). "The targeted intervention of IFI44L can regulate inflammation and control viral replication, which may provide a potential approach for controlling the development of COVID-19." (PMID 35928229, 2022). "Elevated IFI44L, ISG15, and OAS1 mirror transcriptomic patterns reported in psoriatic arthritis and severe COVID-19, suggesting convergent antiviral-like activation." (PMID 40869237, 2025). "Previous research has highlighted the up-regulation of genes such as IFI44L, IFFI44, RSAD2, OAS1, EPSTI1, and OSAL in COVID-19, contributing to immune regulation." (PMID 38601162, 2024). "Specifically, in COVID-19, these genes were CD52, ISG15, and MMP9; in influenza, they included IFI44L, IFIT3, ISG15, and OAS1; and in HIV, OAS1 was identified." (PMID 38601162, 2024). "Therefore, our data raises the question of whether eQTLs activated following an infectious disease could contribute to risk of post-infection sequelae such as recurrent TB, akin to reported hypermethylation in the promoter region of interferon induced protein 44 Like (IFI44L) gene post-COVID-19." (PMID 38870230, 2024). "Conventional ISGs, such as IFI6, IFI44L, LY6E, and ISG15, were markedly increased in COVID-19 patients compared to healthy controls across all major cell types in PBMCs." (PMID 35064122, 2022). "Studies have shown that IFIT2 and IFI44L are strongly induced in bronchoalveolar lavage (BAL) cells and peripheral blood mononuclear cells (PBMCs) of COVID-19 patients, leading to enhance antiviral and immune modulatory functions." (PMID 35922752, 2022). "Some features such as IFI44L in B cells, S100A8 in monocytes, and NCR2 in natural killer cells are involved in the innate immune response of COVID-19." (PMID 35928229, 2022). "Many of the genes previously identified as increased within all cells from COVID-19 participants, e.g., anti-viral factors IFITM3, MX1, IFI44L, and IRF1, are upregulated among SARS-CoV-2 RNA+ cells compared to matched bystanders." (PMID 34352228, 2021). "Another study also reported increased interferon signaling genes including IFI44L, IFIT1, IFIT3 and ISG15, in CD16+ monocytes in COVID-19 cases compared to healthy controls." (PMID 34108966, 2021). "OAS1, OAS2, OAS3, IFIT1, IFIT3, IFI44, IFI44L and IFITM1: Current COVID-19 genetic studies incline to analyze those genes together." (PMID 34109284, 2021). "In our study, we report that IRF7, ISG15, IFI44L, IFIT1, and IFIT3 gene expression is increased in CD16+ monocytes from people with mild COVID-19 compared to healthy controls." (PMID 34108966, 2021).
COVID-19 (continued). "In goblet cells, STAT2 and KLF5 were highly activated and upregulated in many genes with mild/moderate COVID-19, such as ISGs (PARP14 and IFI44L), whereas ELF3, SBP1, NR2F6, and SPDEF were preferentially activated in severe COVID-19 to regulate the expression of their targets." (PMID 37936693, 2023). "For example, IFI44L and USP18 are commonly up-regulated in both DS and COVID-19." (PMID 37379383, 2023). "Although nonsignificant, the severe COVID-19 group in our study did show a higher expression of IFI44L." (PMID 35798818, 2022). "IFI44, OAS1, IFI44L, ISG15, and HERC5 are the five hub genes shared by RA, COVID-19, and SAB." (PMID 36189314, 2022). "An additional 8 targets (CXCL6, IFI44, IFI44L, RSAD2, S100A8, SPRR2A, SYNE1, XAF1) are associated with COVID-19 pathogenesis, but do not have therapies targeting them available for potential repurposing." (PMID 34582497, 2021). "In their study, IFI44L in B cells, S100A8 in monocytes, and NCR2 in natural killer cells were identified as crucial markers that are involved in the innate immune response of COVID-19, while it was also demonstrated that ZFP36L2 in CD4+ T cells can regulate the inflammatory process of COVID-19." (PMID 40163554, 2025). "The intermediate monocytes (consistently present in COVID-19) were characterized by a pronounced antiviral, interferon-driven response, as illustrated by the upregulation of both interferon-inducible and stimulated genes (IFI6, IFI27, IFI44L, and ISG15, SIGLEC1)." (PMID 34424199, 2021).
systemic lupus erythematosus (18 papers, 2017 to 2025). An autoimmune multi-organ disease typically associated with vasculopathy and autoantibody production. "In addition, the promoter methylation of IFI44L is a novel and appropriate diagnostic marker for systemic lupus erythematosus (SLE) patients, with a sensitivity of 88.571% and a specificity of 97.087%." (PMID 35047409, 2021). "Interferon-inducible 44 like (IFI44L) is a newly discovered interferon-induced gene and has been reported to overexpress in systemic lupus erythematosus (SLE)." (PMID 35592687, 2022). "A previous study demonstrated that IFI44L promoter methylation as a blood biomarker for systemic lupus erythematosus." (PMID 35860258, 2022). "IFI44L was identified as a potential genomic biomarker in several autoimmune diseases such as systemic lupus erythematosus, rheumatoid arthritis, and Sjögren's syndrome." (PMID 28881752, 2017). "Upregulated H3K4me3 peaks have been identified in immune response genes in systemic lupus erythematosus (SLE), which correlates with increased expression of immune-related genes such as OAS1 and IFI44L." (PMID 40005847, 2025). "Lupus patients had low methylation and high expression of interferon regulatory genes, including BST2, IFIT3, IFI44L, and IFIT1." (PMID 38753689, 2024). "The hypomethylation of IFN-related genes such as IFI44L and BST2 was correlated with the overexpression of these two genes in total CD4+ T cells from lupus patients." (PMID 34062726, 2021). "Besides, the IFI44L promoter methylation level may also be a potential biomarker of disease activity of SLE, because this gene promoter exhibit significantly increased methylation level in lupus patients in remission stage than in active stage." (PMID 31040845, 2019).